CD24 (CD24 molecule)
Diseases named in the same sentence as CD24 in open-access papers (continued):
Sharing a sentence is not in itself a finding about the gene and the disease.
cancer (continued). "In accordance with these findings, we have demonstrated that CD24+ cells possess cancer stem/progenitor-like properties both in vitro and in vivo." (PMID 27179633, 2016). "Many studies have demonstrated that CD24 was overexpressed in most cancer cells and was closely related to the cancer cell proliferation, invasion and metastasis." (PMID 27494878, 2016). "FACS analysis of cancer cells dissociated from CD24+ control and IGF1R-KD tumors, revealed that IGF1R is essential for the maintenance of stem/progenitors-like cancer cells that fuel the cancer process as recently described." (PMID 27179633, 2016). "In this study, we used cancer stem cell surface marker CD44+/CD24-/low, a first described marker for BCSCs, and embryonic stem cell markers Oct3/4, Sox II and Nanog to determine the putative cancer stem cells." (PMID 27036550, 2016). "Similar to the situation in TNBC (HR 1.93, P=0.02), CD24 expression correlated with a poorer outcome in HR+ cancers (HR 1.91, P=0.01)." (PMID 28721382, 2016). "It is an especially noteworthy feature of CD24 that it marks for an unfavorable outcome in cancers from various tissues, like larynx, lung, Ovary, breast and prostate." (PMID 27276062, 2016). "It is a well-established fact that CD44 and CD24 are often co-utilized along with other tertiary markers to isolate TPCs in various cancers." (PMID 27276062, 2016). "Relapse risks are frequent for particularly aggressive cancer forms which display EMT and invasive properties often associated to CD44high / CD24-/low phenotype and present tumour initiating cell (TICs) features like auto-renewing and chemo-resistance." (PMID 27581651, 2016). "Our results demonstrate that IGF1R-KD specifically in CD24+ cancer cells alters their morphology and phenotype and, more importantly, markedly inhibited their tumorigenic capacity." (PMID 27179633, 2016). "Ergo, CD24 not only is a tissue type specific TIC/CSC marker but a valuable indicator for poor treatment outcome in multiple cancer types." (PMID 27276062, 2016). "Answering this would facilitate the design of better therapeutic strategies, i.e., inhibition/downregulation of CD24 or alternatively exploiting its expression for targeting specific cancer cells." (PMID 26040280, 2015). "Two of these antigens (ALDH1, CD24) were distributed in a nearly ubiquitous fashion on cancer cells." (PMID 25999351, 2015). "As a ligand of p-selectin, CD24 serves as an adhesion molecule that facilitates the metastatic process by supporting the rolling of cancer cells on activated platelets and endothelial cells." (PMID 26040280, 2015). "IC50 values for MitoVES and several other anti-cancer agents for parental and CD24- adherent and sphere Ist-Mes-2 cells." (PMID 25932953, 2015). "The percentage changes of cancer stem like CD44+/CD24- cells in MDA-MB-231 cells and ESA+/CD24- cells in MDA-MB-453 cells 72 h or 96 h after carbon ion beam, X-ray alone or in combination with 25 μM of CDDP were investigated by FACS analysis." (PMID 26338199, 2015). "Recently it was suggested that although CD24 lacks an intracellular domain, it is involved in regulating cancer cell proliferation and gene expression." (PMID 26040280, 2015). "To begin to elucidate the cellular differences between distinct cancer cell subpopulations, we isolated two cancer cell subpopulations based on CD24 expression and phenotypically characterized these cell subsets." (PMID 26040280, 2015). "As expected, injection of CD24− cells resulted in an almost pure CD24− population whereas approximately 40 % of the cancer cells found in the CD24+ inoculated tumors were CD24− cells." (PMID 26040280, 2015). "These cells are CD44+CD24−/low cancer cells and they establish tumors in recipient animals when as few as one hundred cells are transplanted, whereas tens of thousands of cancer cells with a different marker set fail to form tumors." (PMID 26712794, 2015).
cancer (continued). "CD24 expression has been associated with disease progression and cancer-related death in the majority of malignant tumors, although a caveat to these data is that most of these studies are based on the supposedly less specific CD24 clone SN3b." (PMID 26578846, 2015). "We found that the percentages of cancer stem-like CD44+/CD24- cells in MDA-MB-231 cells were dose-dependently increased after 72 h X-ray irradiation, whereas no such clear dose–response was observed after carbon ion beam." (PMID 26338199, 2015). "Because different sub-populations of CD44/CD24 are used to isolate cancer stem cells in different cancer types, we FACS-sorted all four sub-populations and implanted them." (PMID 26449187, 2015). "Taken together, our findings demonstrate that CD24 can serve alone as a marker to identify highly tumorigenic cancer cells with early stem/progenitor-cell properties." (PMID 26040280, 2015). "To further characterize these sphere-forming cells, we examined the presence of two common cancer stem cell surface markers: CD24 and CD44." (PMID 25011053, 2015). "For example, the oncogenic cancer marker CD24 was uniquely expressed in serum-derived exosomes from BrCa patients." (PMID 26601108, 2015). "CD24 is highly expressed in many human cancers, and is often used to identify and enrich CSCs in cancers such as ovarian and pancreatic cancer." (PMID 26464794, 2015). "We report here that CD24 serves as a cell surface marker for highly metastatic tumorigenic cancer cells." (PMID 26040280, 2015). "They observed an elevated expression of CD24 protein in a variety of cancers, including ovarian, breast, bladder, gastrointestinal, endometrial, bile duct, pancreatic, prostate and skin." (PMID 25511546, 2015). "Together, these findings support CD24 as a prognostic marker for carcinoma progression and poorer survival." (PMID 26578846, 2015). "More than ten years ago, CD24 has already been suggested as a novel and promising biomarker for carcinoma progression in NSCLC and several groups have confirmed this finding on protein and transcript level." (PMID 26578846, 2015). "10AT-Her2 cells display a CD44+/CD24-/low phenotype with high levels of the cancer stem/progenitor cell marker proteins nucleostemin, and active aldehyde dehydrogenase-1 (ALDH-1)." (PMID 25209720, 2014). "Since more than 99% of SUM159 cells were CD44+ cells in both monolayer and sphere cultures, we utilized CD24 and EpCAM as additional surface markers to further investigate cancer stem cells." (PMID 25229616, 2014). "These CD24+/CD44+ cells derived from HNSCC cell lines displayed several features typically seen in cancer stem cells, including the ability to differentiate and self-renewal." (PMID 24612587, 2014). "In monolayer culture, the CD24−/EpCAM+ cancer stem cell subpopulation was less than 1% (0.16±0.09%), and the subpopulation was not significantly changed by CDDO-Im treatment (0.18±0.04%)." (PMID 25229616, 2014). "Breast CICs can be characterized by increased expression of CD44 and decreased expression of CD24 (CD44↑/CD24↓) compared to the remaining cancer cells which are referred to as the bulk cancer cells (BCs)." (PMID 25051360, 2014). "Lymph node metastatic OTSCC, express higher CD44/CD24 levels, produce cancer cell spheres in larger number and rapidly (24 hours) compared to node negative OTSCC (1 week) and non-cancer specimens (3 weeks)." (PMID 25685059, 2014). "SUM159 cells formed tumorspheres in culture, and the cancer stem cell subpopulation, CD24−/EpCAM+ cells, was markedly enriched in SUM159 tumorspheres." (PMID 25229616, 2014). "Cancer stem cell immunophenotype studies in oral squamous cell carcinoma indicated that patients with CD24 and CD44 double-positive cells showed the lowest overall survival rate compared to other immunophenotypes." (PMID 24612587, 2014). "The IRS of the cancer cells with membrane CD24 expression ranged from 0 to 12 (median 2.9), with 10/28 (35.7%) cases being positive." (PMID 25240521, 2014).
cancer (continued). "It was shown that FAK deletion in the murine mammary gland suppressed tumorigenesis by decreasing the number of cancer stem cells (CD24+CD29+CD61+ and ALDEFLUOR+ populations)." (PMID 24553076, 2014). "We have demonstrated that HNSCC contain a distinct CD24+/CD44+ cell subpopulation that possesses cancer stem cell-like properties." (PMID 24612587, 2014). "Recent studies have focused on the diagnostic and prognostic significance of CD24 and CD44 expression in human cancers." (PMID 25212506, 2014). "The CD24−/EpCAM+ cancer stem cell subpopulation was markedly increased in sphere culture (12.97±2.95%), which was significantly reduced by CDDO-Im treatment (2.44±0.58%) (p<0.001), an 81.2% inhibition." (PMID 25229616, 2014). "Connecting the deregulation of the BCSCs markers (CD44, CD24) to a possible selection of a more aggressive cancer phenotype by the chemotherapy Regimen 2, basically by the addition of taxanes, is an appealing scenario." (PMID 24632568, 2014). "Although 21.7% of control CaSki cells were CD44+/CD24−, KIAA1199 deficiency dramatically decreased the pool of cancer stem cells as only 2.4% to 6.3% were CD44+/CD24−, depending on the efficiency of the shRNA-mediated depletion of KIAA1199." (PMID 25366117, 2014). "CD24 is also expressed by a range of cell types, but it is commonly affiliated with cancer stem cells." (PMID 24304471, 2013). "Cases that expressed CD24 were positively associated TIII/TIV tumors and with cancer stages III / IV." (PMID 23419168, 2013). "Immunohistochemical analysis clearly indicated that there was a positive correlation between CD24 expression and the pathological cancer grade (low and high) that indicates the degree of malignancy." (PMID 23946784, 2013). "The specific signals of the CD24 protein were localized mainly in the cytoplasm of the cancer cells and were indicated by brown staining." (PMID 23946784, 2013). "CD24 is a cancer stem-like cell biomarker whose expression in tumors is associated with malignant phenotype and poor prognosis of ccRCC and other cancers." (PMID 23442546, 2013). "Kristiansen and colleagues highlighted that several studies analyzed only CD24-membranous expression although CD24-cytoplasmatic expression is usually presented as a prognostic factor for human cancer." (PMID 23419168, 2013). "We analysed the expression of markers for cancer stem cells, CD24 and CD44 by flow cytometry and real time PCR." (PMID 24391839, 2013). "Later, it was also found that rare cancer cells possess the ability to form mammospheres enriched for highly tumourigenic CSCs of the CD44+/CD24-/low phenotype." (PMID 24229464, 2013). "Accumulating evidence suggests that CD24 is a significant marker for cancer metastasis and prognosis." (PMID 23946784, 2013). "CD24 is highly expressed in ovarian, breast, prostate, bladder, renal, non-small cell carcinomas, and other human cancers and is involved in cell adhesion and metastasis." (PMID 23401782, 2013). "The most frequent histopathological type showing this CD44+/CD24- was carcinoma in mixed tumors, followed by tubular, pappilary and solid carcinomas." (PMID 24119896, 2013). "The identified gene sequences encode CD24 and EVL and both have documented established and/or proposed biological functions relevant to cancer cell biology." (PMID 23166783, 2012). "CD24 is highly expressed in ovarian, breast, prostate, bladder, renal, nonsmall cell carcinomas, and other human cancers." (PMID 22693526, 2012). "CD24, a glycosylphosphatidylinostitol-anchored cell surface protein, is expressed in neurons, preB cells, T cells, and several cancer cells and functions in differentiation and activation of granulocytes and B lymphocytes." (PMID 23284858, 2012). "Both CD44 and CD24 are known to contribute to cellular signaling and cell adhesion, and their role in cancer recurrence has been investigated." (PMID 22839505, 2012).
cancer (continued). "CD24 is a small cell surface protein molecule anchored by glycosyl-phosphotidyl-inositol in a wide variety of cancer cells." (PMID 22693526, 2012). "We found that the levels of CD44 and CD24 expression show great variation between cell lines even in cells of the same cancer subtype." (PMID 22693526, 2012). "We mainly focus on analysing the significance of CD44 and CD24 as CSC surface markers in combination or with other putative markers in different types of cancer." (PMID 22693526, 2012). "The percentage of cancer cells with membrane CD24 expression ranged from 0 to 50% (median 0, mean±s.d." (PMID 22333601, 2012). "Flow cytometry was then performed using the human TIC surface markers Lin-, CD24 and CD44, which importantly have also been implicated in TIC characteristics in luminal cancers specifically." (PMID 22765220, 2012). "The variations in CD44 and CD24 proportions from cell line to cell line show the phenotypic heterogeneity in different cancer types." (PMID 22693526, 2012). "We also observed that STAT3 expression in cancer stem cells (CD44+CD24–/low subpopulation) of MCF-7 cells was much higher than that in MCF-7 cells." (PMID 23554768, 2012). "Differently and in spite of its expression in many different cancer subtypes, the ambiguity on CD24 classification and distribution is still persisting." (PMID 22693526, 2012). "At low magnification, a distinctive distribution of the CD44/CD24 population within the cancer tissue was noted." (PMID 23028444, 2012). "Here we show that Taxol, Dox, and 5FU inhibited cancer cell growth, while at the same time, they induced a higher proportion of CD44high/CD24-/low cells from about 2% in the controls to about 6% to 20% in the surviving populations after a 72-hour exposure." (PMID 22309939, 2012). "In particular, the variable pattern of CD24 immunostaining (membrane and cytoplasmic) precluded the precise quantification of the percentage of CD24 membrane-positive cancer cells." (PMID 23028444, 2012). "Earlier studies have identified a subpopulation of putative cancer stem cells (CSCs) with the phenotype CD44+/CD24-/low and more recently, aldehyde dehydrogenase (ALDH) activity was shown to mark normal as well as malignant mammary stem cells." (PMID 21957977, 2011). "Associations between the mRNA expression of CD44 isoforms and the cancer stem cell phenotypes CD44+/CD24- and ALDH1+ (as determined by IHC)." (PMID 21957977, 2011). "Similar results were obtained when CD44 RNA expression levels were compared with the presence of cells with the putative cancer stem cell phenotype CD44+/CD24-." (PMID 21957977, 2011). "We noticed a shift of the RMECs of carcinomas towards the CD24hiCD29hi gate, resembling the CD24/CD29 profile observed in premalignant mammary glands of transgenic MMTV-Wnt1 mice." (PMID 22022542, 2011). "293T cells readily form spheres that are enriched with cancer stem cell surrogates ALDH1 and CD44+/CD24- and express the proteins associated with the epithelial-mesenchymal transition and stem cell developmental pathways." (PMID 20615238, 2010). "We report that 293T cell readily form spheres that are enriched with cancer stem cell surrogates ALDH1 and CD44+/CD24- cells and express proteins associated with the epithelial-mesenchymal transition and stem cell developmental pathways." (PMID 20615238, 2010). "Taken together, the high egfr copy number MDA-MB-468 CD44+/CD24-/LOW cells represent cancer cells with a higher potential for survival, esp." (PMID 20199686, 2010). "Many cancers were found to over-express CD24, indicating that the protein can play an important role in tumorigenesis." (PMID 21311095, 2010). "Cell surface receptor CD29, like CD24, mediates cell to extracellular matrix adhesion and can promote cancer progression by inducing invasion, migration and metastasis." (PMID 21311095, 2010).
cancer (continued). "Although CD44+/CD24- cells were originally described as CSCs, in the same original study, CD44+/CD24+ cancer cells isolated from one patient with comedo (more aggressive) type adenocarcinoma were tumorigenic." (PMID 20691079, 2010). "The results of this study clearly show that a major function of HER2 is to increase the frequency of CD44+/high/CD24- cancer stem cells." (PMID 21044318, 2010). "We, amongst others, have shown that cancer cells that have undergone epithelial to mesenchymal transition (EMT) display the CD44+/CD24- phenotype." (PMID 20691079, 2010). "Flow cytometry data suggested that CD24, a molecule capable of supporting the rolling of monocytes, neutrophils, and metastatic cancer cells, was a likely candidate." (PMID 19247427, 2009). "Examination of CD24 immunostaining identifies the cancer cells, however measured gene expression was high across all cell types for some probe sets (i.e. 209771_x_at) and absent for others (i.e. 1560395_at)." (PMID 18501003, 2008). "The cancer stem cells isolated from tumors are mostly isolated by flow cytometry as the CD44+ CD24-/low lineage cell population." (PMID 19014671, 2008). "CD24 is involved in cellular adhesion processes and signalling pathways in cancer cells that are dependent on interactions with P-selectin." (PMID 18433506, 2008). "The immunohistochemical reactions using antibodies directed to CD24 yielded in cancer cells colour reactions of a membranous localisation (CD24m) or a membranous-cytoplasmatic localisation (CD24c-m), of a variable intensity in individual cases." (PMID 16892043, 2006). "Relevant to this review, CD24 is often overexpressed in human cancers." (PMID 40486886, 2025). "CD24 can promote the progression of cancer by exerting both intrinsic and extrinsic functions." (PMID 40486886, 2025). "Of note, even CD24-positive cancer cells that display various cell “death” indicators (trypan blue staining, annexin V staining, nuclear fragmentation, and detachment from the culture surface) are able to recover and form large colonies under 3D culture conditions." (PMID 40076508, 2025). "During the post-transcriptional modification process of CD24, N-glycosylation serves as a chemical signal that regulates protein sorting, thereby controlling the transmembrane transport of CD24 in cancer cells and ultimately affecting the expression level of CD24 on the cell surface." (PMID 40486886, 2025). "This evidence suggests a close link between CD24 and resistance to cancer treatment." (PMID 40486886, 2025). "The observed increase in mutation load in the low-risk group, alongside the elevated expression of immune checkpoint markers such as CD24, CD28, CTLA-4, and TIGIT in the high-risk group, underscores the complex interplay between genetic mutations and immune escape mechanisms in cancer development." (PMID 40510341, 2025). "CD24 is highly expressed in pancreatic, ovarian, bladder, colorectal and other cancer stem cells." (PMID 40486886, 2025). "The most frequently investigated mechanisms included the dysregulation of the PI3K/AKT/mTOR and MAPK signaling pathways, enhanced DNA damage repair via non-homologous end joining (NHEJ), and the overexpression of cancer stem cell markers such as CD44+/CD24−/low and ALDH1." (PMID 40864743, 2025). "Therefore, we believe that CD24 targeting can be combined with other forms of cancer therapies, including traditional chemotherapy, radiotherapy, or other immunotherapies targeting different pathways or mechanisms, potentially yielding synergistic effects." (PMID 40486886, 2025). "Flow cytometry analysis showed that ATG9A KO did not alter the expression of key phagocytosis checkpoints (MHC-I, PD-L1, CD24, CD47) or the CAR target EphA2, suggesting ATG9A regulates cancer cell susceptibility to macrophage killing through a specific and independent mechanism." (PMID 40595560, 2025).